NAE1 (NEDD8 activating enzyme E1 subunit 1)
Description:
Regulatory subunit of the dimeric UBA3-NAE1 E1 enzyme. E1 activates NEDD8 by first adenylating its C-terminal glycine residue with ATP, thereafter linking this residue to the side chain of the catalytic cysteine, yielding a NEDD8-UBA3 thioester and free AMP. E1 finally transfers NEDD8 to the catalytic cysteine of UBE2M. Necessary for cell cycle progression through the S-M checkpoint. Overexpression of NAE1 causes apoptosis through deregulation of NEDD8 conjugation. The covalent attachment of NEDD8 to target proteins is known as 'neddylation' and the process is involved in the regulation of cell growth, viability and development.
Synonyms: APP-BP1; APPBP1; HPP1; ula-1; A-116A10.1; NEDFIH
Tractability: Small molecule: a drug acting on it is in phase 2 or 3 trials; a structure with a bound ligand is known; a high-quality ligand is known; it has a binding pocket of medium quality; it belongs to a druggable protein family. Antibody: UniProt places it where antibodies can reach, with high confidence; its Gene Ontology location is reachable by antibodies, with medium confidence. PROTAC: UniProt records ubiquitination sites on it; ubiquitination databases record sites on it; its protein half-life has been measured; a small molecule that binds it is known.
Chemical probes: PD084055
Gene: Protein-coding gene on chromosome 16 (66,802,874 to 66,873,256, reverse strand). Ensembl gene ENSG00000159593.
Subcellular location: Cell membrane
Subcellular location (Human Protein Atlas): Nucleoplasm; Centrosome; Microtubules
Pathways (Reactome):
Metabolism of proteins: Neddylation
Gene Ontology:
Molecular function: NEDD8 activating enzyme activity; protein binding; protein heterodimerization activity; ubiquitin protein ligase binding; ubiquitin-like modifier activating enzyme activity
Biological process: mitotic DNA replication checkpoint signaling; neuron apoptotic process; protein neddylation; regulation of apoptotic process; regulation of neuron apoptotic process; signal transduction; regulation of postsynapse assembly
Cellular component: protein-containing complex; cytoplasm; cytosol; glutamatergic synapse; plasma membrane
Genetic constraint (gnomAD): Loss-of-function variants: 35 observed, 54.8 expected, observed/expected ratio (o/e) 0.64, 90% interval 0.49 to 0.85. The upper end of that interval is the gene's LOEUF score, 0.85, which puts it in group 3 of 6, group 1 being the genes least tolerant of losing a copy. Missense variants: 393 observed, 453.98 expected, observed/expected ratio (o/e) 0.87, 90% interval 0.8 to 0.94. Synonymous variants: 149 observed, 152.88 expected, observed/expected ratio (o/e) 0.97, 90% interval 0.85 to 1.12.
Homologues: Orthologues: macaque NAE1 (99% identical), chimpanzee NAE1 (98% identical), dog NAE1 (98% identical), mouse Nae1 (97% identical), rabbit NAE1 (96% identical), rat Nae1 (93% identical), pig NAE1 (90% identical), tropical clawed frog nae1 (76% identical), zebrafish nae1 (73% identical), guinea pig NAE1 (53% identical), Drosophila melanogaster APP-BP1 (45% identical), Caenorhabditis elegans ula-1 (37% identical). Paralogues in human: UBA1 (24% identical), UBA7 (23% identical), UBA6 (21% identical), SAE1 (18% identical), ATG7 (10% identical), UBA3 (8% identical), UBA2 (7% identical), MOCS3 (6% identical), UBA5 (4% identical).
Diseases named in the same sentence as NAE1 in open-access papers:
NAE1 is named in the same sentence as 66 diseases in open-access papers, as found by Europe PMC text mining. Sharing a sentence is not in itself a finding about the gene and the disease. The quoted sentences say what the papers report.
breast carcinoma (7 papers, 2020 to 2024). "We further used immunohistochemical staining to analyze the expression of NAE1 in the breast cancer tissue microarray, which is composed of 129 breast cancers and 77 adjacent tissues." (PMID 36632463, 2023). "Survival analysis showed that breast cancer patients with high NAE1 expression had poorer overall survival and recurrence-free survival." (PMID 37640964, 2023). "To further confirm the clinical role of neddylation in breast cancer progression, we evaluated the expression of a characteristic neddylation E1 (NAE1)." (PMID 36632463, 2023). "Mechanistically, FOXO1-regulated CYP1B1-AS1 affected the heterodimeric enzyme NAE by directly binding to NAE1 to regulate protein neddylation, thereby inhibiting the malignant progression of breast cancer." (PMID 37640964, 2023). "Overexpressed NEDD8 and NAE1 are positively correlated with HER2 expression in human breast cancer." (PMID 36632463, 2023). "Interestingly, HER2 protein expression was positively correlated with that of NAE1, further suggesting the role of neddylation in the progression of clinical breast cancer." (PMID 36632463, 2023). "Similarly, genes MYBL2 and CSE1L with high methylation aberration frequency in breast cancer are both connected to NAE1 with high degree." (PMID 36266635, 2022). "Our study revealed the expression characteristics and biological functions of CYP1B1-AS1 in breast cancer, and proposed the molecular mechanism of CYP1B1-AS1 binding to NAE1 to inhibit neddylation." (PMID 37640964, 2023). "We also found that neither the SPOP-ASCT2 axis, nor NEDD8 and few neddylation enzymes, including E1 heterodimer NAE1/APPBP1, and UBA3/NAEβ, and two E2s, UBE2M and UBE2F is subjected to regulation by glucose deprivation in breast cancer cells." (PMID 35641493, 2022). "NAE1 is overexpressed in TNBC cell lines and in patients compared to other breast cancer subtypes suggesting that NAE1 status is prognostic of MLN4924 treatment response and outcome." (PMID 32166000, 2020). "MLN4924, a selective inhibitor of the key neddylation enzyme NEDD8 Activation Enzyme (NAE1), shows higher sensitivity to both BRCA1-wild type and -mutant TNBCs compared to other breast cancer subtypes." (PMID 32166000, 2020). "Compared with HER2-negative breast cancer, patients with HER2+ tumors have higher NAE1 expression." (PMID 36632463, 2023). "Our results demonstrated that TNBC cell lines show a higher sensitivity to MLN4924 compared to cell lines representing other breast cancer subtypes due to the overexpression of NAE1 in TNBC compared to non-TNBC subtypes." (PMID 32166000, 2020). "However, we believe that other unknown factors may also participate in neddylation pathway activation in breast cancer, because NEDD8‐activating enzyme E1(NAE1), whose expression wasn't regulated by NNMT, was also reported to be highly expressed in breast cancer tissue compared with ANT." (PMID 38126621, 2024).
glioblastoma (6 papers, 2017 to 2024). The most malignant astrocytic tumor (WHO grade IV). "Accordingly, overactivated neddylation and high expression of the NEDD8-activating enzyme 1 (NAE1) have been found in human cancers such as hepatocellular carcinoma, osteosarcoma, glioblastoma, lung cancer, and colorectal cancer." (PMID 33573293, 2021). "NAE1 and UBA3 levels increased in glioblastoma patients; high NEDD8 levels were associated with poor clinical outcomes." (PMID 31771104, 2019). "Several recent studies have observed a correlation between overactivation of NEDD8 pathway components, including NEDD8, UBA3, NAE1, and Ubc12, with cancer progression and poor prognosis in human lung cancers, colorectal cancers, and glioblastomas." (PMID 28475037, 2017). "Our study revealed that TMZ in combination with the NAE1 inhibitor MLN4924 can successfully decrease cell viability and induce apoptosis even in highly TMZ-resistant glioblastoma cell lines." (PMID 37175636, 2023). "Comparing the gene expressions associated with the neddylation pathway in public data including TCGA and Rembrandt, expression levels of the neddylation enzymes NAE1 and UBA3 were higher in glioblastoma than in the normal." (PMID 31771104, 2019).
Alzheimer disease (5 papers, 2010 to 2025). A progressive, neurodegenerative disease characterized by loss of function and death of nerve cells in several areas of the brain leading to loss of cognitive function such as memory and language. "Although most of the genes were involved in several of these pathways, some of them were restricted to Huntington’s disease (AP2B1, CREB3L4, POLR2H and SOD1), to Alzheimer ́s disease (NAE1, FAS) or to Parkinson’s disease (PARK7)." (PMID 24742402, 2014). "In the Alzheimer’s disease pathway, we found genes up-regulated (Apbb1, Atf6, Cacna1d, Calm3, Casp7, Itpr1, Lpl, and Ppp3ca) and down-regulated (Aph1b, Bid, Cycs, Fadd, Fas, and Nae1)." (PMID 28513549, 2017).
heart failure (3 papers, 2020 to 2023). Inability of the heart to pump blood at an adequate rate to meet tissue metabolic requirements. "CM deletion of NAE1, a regulatory subunit of neddylation, in mice CMs caused heart failure and perinatal lethality." (PMID 31985165, 2020). "Findings from GWAS and Mendelian randomization-proteomics identify seven (CAMK2D, PRKD1, PRKD3, MAPK3, TNFSF12, APOC3 and NAE1) proteins as potential targets for interventions to be used in primary prevention of heart failure." (PMID 37429843, 2023). "Mosaic deletion of NAE1, an essential enzyme for neddylation, in neonatal hearts results in the rapid development of cardiomyopathy and heart failure." (PMID 36662623, 2023).
liver cancer (3 papers, 2018 to 2026). An epithelial or non-epithelial malignant neoplasm that arises from the liver. "Pevonedistat, a potent NAE1 inhibitor that blocks protein urmylation in human cells, exhibits strong synergy with cisplatin, an agent known to induce oxidative stress, in killing liver cancer cells effectively." (PMID 42056084, 2026).
osteosarcoma (3 papers, 2021 to 2024). A usually aggressive malignant bone-forming mesenchymal neoplasm, predominantly affecting adolescents and young adults. "Research has shown that the expression levels of NEDD8-activating enzyme E1 (NAE1) and ubiquitin-conjugating enzyme E2M (UBE2M) are significantly higher in osteosarcoma tissues and cells compared to normal bone tissues and cells, potentially contributing to the onset and progression of osteosarcoma." (PMID 39062505, 2024).
ovarian carcinoma (3 papers, 2021 to 2024). A malignant neoplasm originating from the surface ovarian epithelium. "To determine the relationship between the transcription level of NAE1 and the pathological stage of ovarian cancer, we used the GEPIA stage plot." (PMID 33573293, 2021). "A dataset from patients with ovarian cancer showed a strong correlation between NAE1 and CDH1 (r = 0.5, p = 1 × 10−27)." (PMID 33573293, 2021). "Notably, we observed that ovarian cancer down-regulated genes were less affected by decreased NAE1 levels, implicating neddylation in insulin signaling with potential implications for poor prognosis in ovarian cancer patients." (PMID 38272982, 2024). "The mRNA expression of NAE1 was negatively related to the tumor stage of ovarian cancer." (PMID 33573293, 2021). "In particular, the expression of NAE1 was significantly downregulated in ovarian cancer samples." (PMID 33573293, 2021). "Other studies showed that NAE1 inhibitor MLN4924 may function as a novel chemosensitizer in various types of cancer such as esophageal squamous cell carcinoma, ovarian cancer, cervical carcinoma, and urothelial carcinoma." (PMID 37175636, 2023).
pancreatic cancer (3 papers, 2022 to 2024). "Moreover, correlation analysis revealed that the mRNA levels of NEDD8 and NAE1, Ubc12, and Rbx1 had a statistically significant association with pancreatic cancer." (PMID 35155257, 2022). "In pancreatic cancer overexpression of NAE1 has even been shown to be responsible for cisplatin resistance." (PMID 37024667, 2023). "NAE1 was also overexpressed in pancreatic tumor tissues vs. normal tissues." (PMID 35155257, 2022).
acute liver failure (2 papers, 2022 to 2024). Rapid deterioration of liver function causing encephalopathy and coagulopathy. "Here the authors report that hepatic neddylation deficiency via genetic deletion of NEDD8 Activating Enzyme E1 Subunit 1 (NAE1) causes acute liver failure due to mitochondrial dysfunction and aberrant activation of NF-κB-inducing kinase in mice." (PMID 36526632, 2022). "Treatment with N-acetylcysteine, a glutathione surrogate and antioxidant, has been found to significantly reduce hepatic NAE1 expression to prevent liver inflammation, fibrosis, and injury in the acute liver failure mouse model." (PMID 39697538, 2024). "Dysregulation of NAE1, a regulatory subunit of NAE E1, has been observed in human acute liver failure; loss of NAE in the hepatocytes results in hepatocyte death, inflammation, fibrosis, and eventually liver dysfunction in the mouse model." (PMID 39697538, 2024). "Herein, we show dysregulated expression of NAE1, a regulatory subunit of the only NEDD8 E1 enzyme, in human acute liver failure." (PMID 36526632, 2022).
COVID-19 (2 papers, 2022 to 2026). A disease caused by infection with severe acute respiratory syndrome coronavirus 2. "In a murine model of severe COVID-19, inhibitors of NAE1 and FGFR1 significantly decreased viral load and lung pathology." (PMID 41585476, 2026). "Both NAE1 and FGFR inhibitors reduced viral load and lung damage in a mouse model of severe COVID-19." (PMID 41585476, 2026). "Indeed, inhibition of NAE-1 by MLN4924 resulted in a more significant response in intracellular NEDD8 levels and neddylated secretome analyzed by both western blot and ELISA in COVID-19 patients than in samples from healthy individuals." (PMID 35831294, 2022).
diabetes (2 papers, 2021 to 2025). "Our findings further revealed that both pharmacological inhibition of neddylation using MLN4924 and genetic knockdown of NAE1 mitigate renal fibrosis in mouse models of streptozotocin-induced diabetes and unilateral ureteral obstruction (UUO)." (PMID 39900822, 2025). "Taken together, accelerated neuroblastoma cell loss following exposure to autoantibodies in diabetes, TBI and TBI plus DM from patients having co-morbid Parkinson’s disease, or dementia may be mediated by neuroapoptosis involving (in part) increased Casp3, Bnip3 and Nae1 gene expression." (PMID 34013450, 2021).
lymphoma (2 papers, 2024 to 2025). A malignant (clonal) proliferation of B- lymphocytes or T- lymphocytes which involves the lymph nodes, bone marrow and/or extranodal sites. "For example, MLN4924 inhibiting NAE1 activity exhibits cytotoxic activity against a variety of human tumor-derived cell lines, induced apoptosis or senescence in human lymphoma cells." (PMID 38177106, 2024). "MLN4924 was specifically designed as a first-in-class pharmacological inhibitor of NAE1 and has been investigated in various phase I–III clinical trials for leukemia, lymphoma, and advanced solid tumors." (PMID 39900822, 2025).
prostate carcinoma (2 papers, 2014 to 2019). A carcinoma that arises from epithelial cells of the prostate gland. "The results from our experiment support the hypothesis that FKB’s inhibitory effect on prostate cancer cells is due to FKB’s binding to the NAE1 regulatory subunit APP-BP1." (PMID 30885218, 2019).
renal cell carcinoma (2 papers, 2022 to 2023). "These 27 CTTs including 8 genes CTNNA1, PSMB6, PSMD12, SESN2, SLC22A2, UBE2J2, and NAE1 appeared in the SL pairs of renal cell carcinoma in previous literature studies." (PMID 38074121, 2023).
viral infection (2 papers, 2021 to 2026). "Taken in combination, these results show that nae1 is the likely causative gene underlying the major IPN QTL, which further highlights the extensive role of neddylation in immune response to a broad range of viral infections." (PMID 34547402, 2021). "Inhibition of nae1 activity using a small molecular inhibitor (MLN4924) has been shown to have broad-acting anti-viral activity and to inhibit the replication of several DNA and RNA viruses in vitro, highlighting the importance of the neddylation process during viral infection." (PMID 34547402, 2021).
atherosclerosis (1 paper, 2021). A disease characterized by the build-up of fatty material and calcium deposition in the arterial wall resulting in partial or complete occlusion of the arterial lumen. "Previous studies have shown that MLN4924, an inhibitor that targets NAE1, provides protection against endothelial dysfunction in response to oxidative injury, halts early atherosclerosis, and inhibits inflammation in macrophages and ECs." (PMID 34220539, 2021). "Small molecule inhibitors of NEDDylation activating enzyme 1 (NAE1) may therefore represent a novel therapy for endothelial dysfunction and atherosclerosis." (PMID 34220539, 2021).
cardiomyopathy (1 paper, 2023). A disease of the heart muscle or myocardium proper. "Since the deletion of NAE1 occurred in the critical time window of CM maturation, we hypothesized that disruption of CM maturation underlies the pathogenesis of cardiomyopathy in NAE1F/F hearts receiving high-dose AAV-Cre." (PMID 36662623, 2023).
chondrosarcoma (1 paper, 2018). A malignant cartilaginous matrix-producing mesenchymal neoplasm arising from the bone and soft tissue. "The chondrosarcoma cell lines jj012 and sw-1353 exhibited higher NAE-1 expression than the normal chondrocyte cell line, C28/I2." (PMID 30586948, 2018).
chronic kidney disease (1 paper, 2025). Impairment of the renal function secondary to chronic kidney damage persisting for three or more months. "We here demonstrated that two key components of the neddylation pathway—NEDD8-activating enzyme E1 subunit 1 (NAE1) and NEDD8—are significantly upregulated in human chronic kidney disease (CKD) specimens compared to healthy kidneys, implicating neddylation in CKD-associated fibrosis." (PMID 39900822, 2025).
chronic myeloid leukemia (1 paper, 2026). "Furthermore, NAE1-mediated neddylation of cullins depletes CRL substrate p27kip1 in the nucleus, thereby retaining leukemia stem cells and conferring imatinib resistance in chronic myeloid leukemia (CML)." (PMID 41540013, 2026).
female infertility (1 paper, 2025). Diminished or absent ability of a female to achieve conception. "In addition, NAE1 ablation has been concomitantly associated with female infertility, which prompted us to perform histological analysis of ovaries." (PMID 40083933, 2025). "However, a subsequent evaluation at 18 weeks revealed a complete absence of ovarian follicles in in Nae1-SKO mice, implicating a potential dysregulation of NAE1-mediated pathways in the aberrant development of oocytes and premature ovarian insufficiency, culminating in female infertility." (PMID 40083933, 2025).
Hepatic steatosis (1 paper, 2022). Steatosis is a term used to denote lipid accumulation within hepatocytes. "Hepatic steatosis is more obvious in adult NAE1-deleted livers, which may result from a more severe mitochondrial dysfunction." (PMID 36526632, 2022).